EGF (epidermal growth factor)
Diseases named in the same sentence as EGF in open-access papers (continued):
Sharing a sentence is not in itself a finding about the gene and the disease.
tumor (continued). "In conclusion, molecules and growth factors released by activated platelets (EGF, PDGF, TGF-β, IGF and CCL5) may protect tumor cells from chemotherapy by promoting the expansion of ALDH+ and CD133+ OvCa-CSCs, favoring drug resistance and tumor relapse." (PMID 33809553, 2021). "Compared to other previous protocols of glioblastoma organoids, the authors dissected tumor tissues into approximately 1 mm fragments without the addition of extracellular matrix or EGF and bFGF and cultured them on an orbital shaker for 1–2 weeks to generate 3D structures." (PMID 33572835, 2021). "The proliferation and metastasis of tumor cells can be promoted by M2 macrophages by releasing anti-inflammatory factors such as IL-10 and TGF-β, immunosuppressive factors such as PGE2, arginase-I, somatomedins such as EGF, CCL18, and HIF-1α and pro-metastasis factors such as MMPs, uPA, and uPAR." (PMID 34506209, 2021). "Interestingly, while Gene 33 acts as a tumor suppressor in in situ breast tumor cells, it is required for prevention of apoptosis and for metastasis of MDA-MB-231 breast cancer cells by inhibiting EGF-dependent inhibition of metastasis." (PMID 34206547, 2021). "Fcy-hEGF fusion protein, composed of yeast cytosine deaminase (Fcy) and human EGF (hEGF), is capable of binding to EGFR and enzymatically convert 5-fluorocytosine (5-FC) to 1000-fold toxic 5-fluorocuracil (5-FU), thereby inhibiting the growth of EGFR-expressing tumor cells." (PMID 33672989, 2021). "The EGF DCX/RSV LPHNPs also showed a better antitumor activity compared to free drugs and DCX/RSV LPHNPs using a lung cancer-bearing mice model, as indicated by the lower tumor volume, higher tumor growth inhibition ratios and absence of weight loss in mice." (PMID 33499040, 2021). "We assume that because EGF and TGF-α both promote the proliferation of human tongue epithelial cells and tumor cells, it leads to the noncausal association between thick tongue fur and tumor marker abnormality." (PMID 34887933, 2021). "The conjugate with EGF (P-EGF-Cy7) exhibited no significant accumulation in the tumor over time." (PMID 31906300, 2020). "The data indicated that EGF-PLGA@5Fu/PFC NPs exhibited better antitumor efficacy than the other formulations evaluated in this study, as evidenced by enhanced suppression of cell proliferation, induction of cell apoptosis and attenuation of tumor growth in vitro and in vivo." (PMID 32345258, 2020). "Also, the discrepancies between the tumour size observed after xenografting iSOX11 cells via the mammary fat pad model and the MIND model, as well as the finding that EGF can decrease MEX3A levels, suggest an influence of microenvironmental factors on SOX11 tumour cell behaviour." (PMID 32909943, 2020). "Consequently, EGF can induce an upregulation of vascular cell adhesion molecule-1 (VCAM-1) that favors the interaction between TAMs and tumor cells, which in turn promoted tumor cell invasion." (PMID 32322199, 2020). "We hypothesized that this invasion kinetics can be associated with the release or cell–ECM interaction of crucial growth factors (e.g., VEGF, TGF‐β1, EGF, IGF) involved into the stimulation of cellular invasion and migration during tumor growth and metastasis development." (PMID 32274296, 2020). "The tumor growth rate in mice treated with EGF-PLGA@5Fu/PFC NPs was significantly lower than that in the groups treated with free 5Fu, PLGA@5Fu NPs and PLGA@5Fu/PFC NPs, and the different formulations that contained 5Fu induced a trend toward a decrease in tumor growth rate." (PMID 32345258, 2020). "Taken together, the positive feedback loop between EGF/EGFR and UPR may cooperate for the survival of cancer cells in hazardous microenvironments and the stimulation of tumor angiogenesis, ultimately resulting in tumor relapse." (PMID 32630838, 2020).
tumor (continued). "Genes related to cancer pathways were downregulated upon atezolizumab treatment, including angiogenic factors for tumor vascularization (TNK1, AREG and KDR), proto-oncogenes (RET and MET) and tumor cell survival/migration/invasion (CDH1, RARA, WNK2, WNT4A, WNT9A, TGFB2, EGF, and LAMA3)." (PMID 32616706, 2020). "Not only epidermal growth factor (EGF)-mediated glycosylation, which could inactivate GSK3β, but also COP9 signalosome 5 (CSN5)-mediated deubiquitination induced by TNF-α, stabilized PD-L1 expression on tumor cells." (PMID 32290052, 2020). "In contrast, dying tumor cells can stimulate the production of TNF-α, epidermal growth factor (EGF), IL-6, and Wnt ligands, which in turn recruit myeloid cells and fibroblasts to the local TME, serving as anti-cell death signals and decreasing the efficacy of anti-tumor therapies." (PMID 32973519, 2020). "Moreover, some reports showed that EGF promotes epithelial-mesenchymal transition (EMT), which could contribute to the migration/metastasis of tumor cells, and resistance to chemotherapy or hormonal therapy." (PMID 31620367, 2019). "As a tumor is often described as being like a “chronic wound”, the hypoxic conditions and high concentration of cytokines and growth factors IL-1α, IL-1β, IL-6, FGF-2, IGF-1, TGF-β, VEGF-A, HIF-1α, EGF, TGF-α are a likely trigger for MSCs recruitment to tumor microenvironments." (PMID 31569731, 2019). "Inhibition of EGF/EGFR signaling by the widely utilized anti-tumor drug gefitinib greatly inhibited TGIF2WT-promoted metastasis of H1299 xenografts as monitored in vivo by the luciferase assay, which was further confirmed by counting the tumor burden shown by HE staining." (PMID 31871777, 2019). "Interestingly, immunofluorescence revealed amplified EGF expression in heterospheroids, which was not readily apparent in homospheroids, solitary tumor cells, or CAFs." (PMID 30710055, 2019). "PD-L1 expression in tumor cells can be constitutive or inducible and may vary over time in response to different stimuli such as interferon (IFN)-γ, epidermal growth factor (EGF) or cytokines." (PMID 31075880, 2019). "However, it is difficult to extrapolate these results to the in vivo setting since EGFR might respond not only to EGF but also to TGF-α, AR, EPGN, BTC, HB-EGF and EREG, which are also increased in tumor tissues." (PMID 31921216, 2019). "In addition, tumor cells were also reported to overcome IGF1R inhibition in an EGFR-dependent manner, indicating that EGF signaling could be another way mediating IGF1R blockade resistance." (PMID 30422809, 2019). "Knockdown of NEDD4 diminished both the EGF- and the non-EGF-dependent cell migration capacity evaluated by penetration of micro-pores of the membrane in the transwell, which resembles the escaping process of tumor cells from tumor tissues into blood stream." (PMID 29455656, 2018). "In addition, pro-angiogenic molecules secreted by tumor cells under hypoxic conditions, including vascular endothelial growth factor (VEGF), platelet-derived growth factor (PDGF), epidermal growth factor (EGF), and MMPs, can activate their receptors on the surface of ECs and trigger angiogenesis." (PMID 30618749, 2018). "Interestingly, the antibodies did not provide further benefits even when they were used together with MIT, implying that PC3 tumours grow in a largely EGF/EGFR axis-independent manner in the absence of surrounding stromal cells." (PMID 30333494, 2018). "Also, data suggest EGF 50 ng/ml and folic acid 6 mg/L to be beneficial for individual tumor viability and not proliferation." (PMID 29861851, 2018). "Additionally, they found that 7A7 could inhibit EGF-induced EGFR signaling in D122 tumour cells, triggering tumour regression in a T-cell dependent manner." (PMID 29552307, 2018). "Importantly, combined administration of trametinib and EGF also facilitated an apoptotic switch in EGFR-transformed primary tumor cells, but not normal mammary epithelial cells." (PMID 30250119, 2018).
tumor (continued). "The TME not only plays a supporting role for various cells, including tumor cells, immune cells, vascular endothelial cells, and fibroblasts but also forms the ECM (including collagen, laminin, and proteoglycan complexes) and secretes multiple cytokines, such as SDF-1, IL-6, bFGF, and EGF." (PMID 30355650, 2018). "Indeed, in the first-in-humans trial using 111In-EGF tumor, localization was achieved without any serious adverse effects." (PMID 29959216, 2018). "Towards this end, KO/PyMT and WT/PyMT tumour cells were grown in 10% fetal bovine serum (FBS)-media in the presence/absence of high concentrations of HSPG-binding growth factor FGF2 or non-HSPG-binding growth factor EGF." (PMID 28102194, 2017). "Both semi-quantitative and quantitative PCR analysis demonstrated that Epidermal Growth Factor (EGF), Fibroblast Growth Factor (FGF), and Insulin-like Growth Factor (IGF-1) (factors known to support growth of cancer cells) were expressed by both primary tumor and brain metastasis CAFs." (PMID 28649646, 2017). "However, the mechanism by which EGF-EFGR signaling induces tumor cell death has not yet been fully described." (PMID 27935858, 2017). "In addition, upon comparing the gene expression profile of tumor tissue with that of background nontumor liver, the EGF- and VEGF-mediated pathways were distinctively elevated in HCC." (PMID 28968425, 2017). "On the other hand, cetuximab could reduce the angiogenesis function of EGF so that tumor could not get enough supports from vessels for its growth." (PMID 29390545, 2017). "Thus, our findings that KO/PyMT tumour cells are deficient in proliferative responses to HSPG-dependent (FGF2), but not HSPG-independent (EGF) growth factors are consistent with the possibility that α3(V) chains aid GPC1 co-receptor function." (PMID 28102194, 2017). "We therefore assessed whether EGF increased proliferation and survival in normal and cancer cells after radiation treatments and found that EGF induced cell death in EGFR1-overexpressing tumor cells." (PMID 27935858, 2017). "Interestingly, EGF stimulates anterograde lysosome trafficking through a different mechanism than previously reported for HGF, suggesting that there are redundant signaling pathways that control lysosome positioning and trafficking in tumor cells." (PMID 28978320, 2017). "Both EGF and basic FGF are involved in signaling through the Ras/Raf/MAPK and PI3K/Akt pathways via different mechanisms to control gene expression, cellular proliferation, cell motility, differentiation and inhibition of apoptosis, which contributes to tumor development." (PMID 27505250, 2016). "The most frequently described proangiogenic tumor “switch on” factors include vascular endothelial growth factors (VEGFs), fibroblast growth factor (FGF), platelet-derived growth factor (PDGF), transforming growth factors (TGFs), epidermal growth factor (EGF), angiopoietins (Angs), and others." (PMID 27965519, 2016). "Using whole tumor transcriptome sequencing, we show for the first time that the transcriptome of HBL tumors which required liver transplantation is enriched most for cancer signaling pathways, in which the larger proportion of differentially expressed genes participate in EGF and ERBB signaling." (PMID 27910913, 2016). "The multiple level of interactions that exist in EGF signaling, RAS, and cell survival, proliferation and invasion, indicated that high plasma TIMP-1 levels may interact with EGFR signaling and thereby affect the anti-tumor effects of EGFR inhibitors." (PMID 27509063, 2016). "In addition, COX-2 is an early gene that is rapidly induced by pro-inflammatory cytokines (interleukin (IL) 1β, IL2 and tumor necrosis factor (TNF)), growth factors (EGF and platelet-derived growth factor (PDGF)), lipopolysaccharides, bile acids, ultraviolet B irradiation and tumor promoters." (PMID 25595899, 2015).
tumor (continued). "Thus, the application of epidermal growth factor (EGF), which is one of several natural ligands for EGFR, could help cover all of the subsets of tumor cells that express wild-type EGFR, as well as its mutant forms." (PMID 28347118, 2015). "Thus, PDPN may present an opportunity to interrupt oncogenic signaling cascades that induce its expression such as those initiated by a number of tumor promoters including Ras, FGF/BMP, Src, EGF, and TGFβ." (PMID 25826087, 2015). "In addition, DIDS and H2DIDS reduced hepatocyte growth factor (HGF)-induced, but not epidermal growth factor (EGF)-induced, cell scattering, wound healing, and 3-dimensional (3D) proliferation of tumor cell spheroids." (PMID 26543230, 2015). "Indeed, within the primary tumor microenvironment, the stromal cells provide potent oncogenic signals, such as TGF-β, HGF, epidermal growth factor (EGF), Wnt, and β-fibroblast growth factor (FGF), which stimulate cancer cell proliferation, survival, and invasion, thus facilitating metastasis." (PMID 28536400, 2015). "Cancer pain can be caused by different mediators: immune system cells infiltrating the tumor: neutrophils, T cells, and macrophages secrete prostaglandins, endothelin, TNF-α, Transforming Growth Factor (TGF), IL-1 and IL-6, Epidermal Growth Factor (EGF), and Platelet Derived Growth Factor (PDGF)." (PMID 26538839, 2015). "Additionally, GDI2, a protein functioning in the cycling of Rab GTPases and arginase II, i.e. a non-liver isoform of the urea cycle were up-regulated in tumours of EGF transgenic mice." (PMID 25872475, 2015). "HMT3522-T4-2_LBNL (T4-2) cells were generated from S1 cells by a multi-step process: 238 passages in medium without EGF followed by transplantation into a mouse which generated a tumor, and T4-2 cells were isolated from the serial passage of this tumor; thus T4-2 cells are malignant and tumorigenic." (PMID 25057922, 2014). "Thus, according to these authors, this growth factor cannot be used for quick and correct orientation in clinical condition of patients in the early stages of tumor growth, unlike epidermal growth factor (EGF)." (PMID 24591761, 2014). "Additionally, other tumor-targeting ligands, including antibodies, peptides and proteins (TRAIL and EGF) may be conjugated to the nanoparticles." (PMID 25113279, 2014). "It has been reported that epidermal growth factor, platelet-derived growth factor, stromal cell-derived factor-1/CXCR4, SCF/c-Kit and vascular endothelial growth factor (VEGF)/VEGF receptor (VEGFR) 1 and VEGFR2 may play a role in the tumor-tropic effects." (PMID 24040358, 2013). "By the protein array study, we demonstrate that many growth factors which promote tumor cell survival and metastasis are over-expressed in a time-dependent manner in the hydronephrotic urine, including beta-FGF, IFN-γ, PDGF-BB, PIGF, TGF-β, VEGF-A, VEGF-D and EGF." (PMID 24023933, 2013). "Moreover, under high EGF concentrations, tumor cells did not retain EGFR amplification and lost tumorigenicity in vivo." (PMID 24294177, 2013). "These experiments measured EGF-NIR binding, as would be viewed through an endoscope, and estimated the ratio between the signal of a carcinoma culture (COLO205, A431) to background binding (IEC6), in order to optically distinguish between tumor and normal tissues." (PMID 23857061, 2013). "Consequently, we examined cell migration under various doses of EGF in both adenocarcinoma cells (MTLn3) and non-metastatic cells taken from the same tumor (MTC)." (PMID 22577847, 2012). "Some investigators have found that fluorescence signal persisted for 4 to 5 days post injection of fluorescent agent, but in current experiment, EGF-Cy5.5 signal was barely detectable in the tumor site 96 h post injection, with no indication of signal accumulation with serial use." (PMID 23029451, 2012). "Similarly, active EGF signaling in SPC-expressing cells only led to alveolar tumor development and not BASC hyperplasia or neoplasia." (PMID 23285300, 2012).
tumor (continued). "A significant linear relationship was found between the obtained tumor BLI and FLI signals from each of the four probes: Prosense680 (r = 0.73, p<0.01), IRDye 800CW 2-DG (r = 0.70, p<0.01), MMPSense680 (r = 0.92, p<0.0001) and IRDye 800CW EGF (r = 0.88, p<0.0001)." (PMID 22348134, 2012). "While integrin αvβ5 is unable to initiate cell migration/invasion in the absence of growth factor stimulation, stimulation of tumor cells with EGF selectively enhances the ability of cells expressing integrin αvβ5 to invade on vitronectin in vitro and metastasize in vivo." (PMID 22586492, 2012). "High levels of EGF within the tumor may possibly be responsible for receptor activation and suggest the possibility to obtain anticancer activity against LMS through the direct inhibition of EGF." (PMID 23056514, 2012). "In addition, regulation of GSC division frequency is a specific role for EGF signaling as it is not affected in all tumor models." (PMID 22586473, 2012). "EGFR and Her-2 were not considered to be valuable salivary tumor markers in OSCC, however, lower levels of EGF in saliva may suggest a higher susceptibility for OSCC development." (PMID 20429940, 2010). "While this SingleQuots® may have contributed to the VEGF production in these tumor types, the other analytes (IL-8 and bFGF) induced by EGF did not correlate by tumor type (data not shown)." (PMID 18616824, 2008). "However, blockade of P38 MAPK inhibited EGF induction of both NRP-1 and VEGF and might be a therapeutic target in this tumour system." (PMID 12618892, 2003). "Consequently, it can be concluded that EGF/TGF-alpha-LA produced by human tumour cells is mainly TGF-alpha rather than EGF." (PMID 2736210, 1989). "In addition, we observed that EGF treatment barely impacted OX40 expression in T cells from tumor tissues, which might due to the negligible levels of EGF receptor (EGFR) gene expression in T cells compared with tumor ECs." (PMID 40026246, 2025). "Moreover, the number of proliferative T cells in tumor tissues was not influenced by serum EGF." (PMID 40026246, 2025). "We hypothesize that epiregulin (EREG), an epidermal growth factor (EGF) family member derived from hepatic stellate cells (HSCs) and activated by LPS stimulation, is a crucial mediator of HCC progression with epidermal growth factor receptor (EGFR) expression in the tumor microenvironment." (PMID 38673992, 2024). "In addition, the degradation of the ECM by MMPs produces the activation of peptides, such as the epidermal growth factor (EGF) which promotes the proliferation of its receptor (EGFR), involved in the signalling of integrin and growth factors, similar to insulin that stimulates tumour progression." (PMID 38203696, 2023). "Since EGF, a ligand of receptor tyrosine kinase, is widely reported to promote tumor growth, cell proliferation and apoptosis deregulation through activation of its downstream signaling, including MEK/ERK, we clarified whether 22-(4′py)-JA was able to suppress MEK/ERK signaling mediated by EGF." (PMID 36558080, 2022). "CBD suppresses the activation of the EGF/EGFR signaling pathway and its downstream targets Akt, ERK and NF-κB in multiple tumor cells, which demonstrates that there might be a potential role for CBD to interfere in the cross-talk between inflammation, cell survival and tumor proliferation." (PMID 33921049, 2021). "Therefore, drugs targeting EGF, IGF-1, and HGF may critically disrupt not only tumorigenesis and progression of HCC but also angiogenesis, and counteract the metastasizing potential of the tumor." (PMID 34572344, 2021). "The obtained GBOs are cultured in specific medium without exogenous use of epidermal growth factor, fibroblast growth factor, serum and no exogenous extracellular matrix to maintain their cell-cell interactions, subtypes and gene expressions of the parental tumour." (PMID 32512726, 2020).